SIRT1 (sirtuin 1)
Diseases named in the same sentence as SIRT1 in open-access papers (continued):
Sharing a sentence is not in itself a finding about the gene and the disease.
colitis (continued). "While this study demonstrates Eng’s potential to mitigate experimental colitis via AMPK/SIRT1/PGC-1α-mediated mitochondrial restoration, certain limitations highlight areas beyond the current scope." (PMID 40427406, 2025). "Restoration of AMPK and SIRT1 activity or overexpression of PGC1α has been shown to ameliorate experimental colitis in animal models by suppressing inflammation, enhancing barrier function, and reducing oxidative damage." (PMID 40613788, 2025). "Clinical and experimental studies have proven that SIRT1 is down-regulated in UC, and SIRT1 activators have the ability to improve colitis symptoms." (PMID 40076434, 2025). "In this study, we used a DSS-induced mouse model to explore the effect of smooth-muscle-specific SIRT1 overexpression on colonic epithelial proliferation and renewal in mice with colitis." (PMID 40076434, 2025). "Specifically, SIRT1 K408Q knock-in mice exhibited a protective phenotype against dextran sulfate sodium (DSS)-induced colitis, highlighting the significance of SIRT1 in modulating intestinal inflammatory responses." (PMID 41356121, 2025). "In the present study, we conducted a dextran sulfate sodium (DSS)-induced experimental colitis model using Sirt1-Tg mice and showed that Sirt1-Tg mice displayed much more severe inflammation." (PMID 40076434, 2025). "We showed that the expression of cZFP609 was higher in DSS-induced colitis of Sirt1-Tg mice than in WT mice." (PMID 40076434, 2025). "We show that Sirt1-Tg mice have more secretion of cZFP609 in DSS-induced mouse colitis, thus, they detained HIF-1α in the cytoplasm." (PMID 40076434, 2025). "Antioxidant defence components, inflammation, and cell death are all regulated by SIRT1 and are responsible for enhancing the maintenance of inflammatory cells in colitis." (PMID 38796570, 2024). "This discovery underscores the pivotal and irreplaceable role played by SIRT1 K408 acetylation in orchestrating the anti‐inflammatory potency of aspirin within the context of DSS‐induced colitis murine models." (PMID 38482749, 2024). "To investigate the role of SIRT1 in colitis development, specifically its impact on the Treg/Th17 balance, we utilized EX-527 in subsequent in vivo studies." (PMID 39867884, 2024). "SIRT1 regulates the tri-methylation of H3K9 (H3K9me3) in colitis and deacetylates the acetylated forms of H3K56 and H3K4 in cancer cells." (PMID 37513404, 2023). "Icosapent alleviates acetic acid-induced rat colitis by modulating SIRT1 pathway, reducing inflammation, oxidative stress, and apoptosis." (PMID 37868958, 2023). "Data from several studies show that peneth and goblet cells increase in gut-specific knockout SIRT1 mice, alleviating colitis and preventing CRC by remodeling the gut microbiota." (PMID 37371959, 2023). "Catalpol reduces endoplasmic reticulum stress and upregulates SIRT1 in TNBS-induced colitis animals." (PMID 37371959, 2023). "We found a significant decrease in both the mRNA and protein levels of SIRT1 in mice undergoing experimental colitis, which is consistent with published reports." (PMID 37744380, 2023). "In order to assess if NR treatment restores the SIRT1-PGC1α axis during experimental colitis, we assessed the expression levels of SIRT1, PGC1α, and TFAM in DSS+NR and DSS+Vehicle mice." (PMID 37744380, 2023). "Similar to human UC, we found that both the mRNA and protein levels of SIRT1 were significantly decreased within the intestinal epithelium of mice undergoing experimental colitis as compared to control mice." (PMID 37744380, 2023). "Mitigation of DNBS-induced colitis damage is achieved through the modulation of the NF-κB/Nrf2/SIRT1 signaling pathways." (PMID 37359553, 2023).
colitis (continued). "Evidence from multiple studies has demonstrated that agents that stimulate SIRT1/FoxO3a/Nrf2 pathway are effective in dampening the flares of colitis." (PMID 37111290, 2023). "In TNBS-induced colitis mice, resveratrol administration upregulated SIRT1, activated the antioxidant program related to NF-E2-related factor (NRF2), and inhibited NF-κB signaling." (PMID 37371959, 2023). "SIRT1 inversely correlates with SIRT1 expression during IBD treatment against DSS-induced colitis in mice." (PMID 36677021, 2023). "In contrast, SIRT1 deletion or silencing suppresses colitis and maintains gastrointestinal homeostasis by inducing Tregs." (PMID 37483618, 2023). "We demonstrated that NR treatment restored the SIRT1-PGC1α axis during DSS colitis and resulted in increased mitochondrial complex activity." (PMID 37744380, 2023). "Among them, SIRT1, a sirtuin of nuclear origin, is associated with the pathogenesis of IBD in various experimental models of colitis." (PMID 36359214, 2022). "Overall, COS can improve colitis by regulating intestinal microbiota and the PPARγ/SIRT1-mediated NF-κB pathway." (PMID 35200626, 2022). "Many studies found that the low expression of SIRT1 led to increased acetylation of NF-κB p65 in colitis models and promoted the inflammatory response." (PMID 35958178, 2022). "SIRT1/PPAR-γ signaling was suggested to play a fundamental role in the pathogenesis of DSS-induced colitis." (PMID 35631426, 2022). "Another study showed that geniposide alleviates inflammatory responses in colitis via the AMPK/SIRT1 signaling pathway." (PMID 35883477, 2022). "SIRT1 levels were significantly higher in the SI-treated group than those of mice in the colitis group." (PMID 36359214, 2022). "Intervention with SirT1 activators such as Cay10591 or SRT1720 has been reported to be able to activate intestinal SirT1 to prevent and cure experimental colitis." (PMID 36615829, 2022). "SIRT1 expression in the murine colonic mucosa of mice in the colitis group was lower than that of mice in the control group." (PMID 36359214, 2022). "Immunohistochemical staining showed that SIRT1 was significantly upregulated in colon mucosa samples from SI-treated mice compared to those of mice in the colitis group." (PMID 36359214, 2022). "We evaluated changes in SIRT1 levels in the colon of the control, colitis, and SI-treated groups using qRT-PCR." (PMID 36359214, 2022). "In contrast, the deletion or silencing of SIRT1 inhibits colitis through the induction of Tregs, which are essential for the maintenance of gastrointestinal homeostasis." (PMID 34887866, 2021). "Additional research to clarify the association between AGER1, RAGE, Sirt1, HFD and colitis is warranted." (PMID 34380504, 2021). "In rats with DDS-induced colitis, SIRT1 activator pretreatment corrects colonic dysbiosis and reduces systemic and colonic mucosa inflammation." (PMID 33513830, 2021). "Treatment with resveratrol significantly improves DSS-induced colitis and restores the SIRT1 mRNA levels." (PMID 34887866, 2021). "In a mouse colitis model, transferring naïve CD4+ T cells into mice with DCs with a specific deletion of SIRT1 aggravated colonic inflammation and promoted weight loss." (PMID 34887866, 2021). "SIRT1 induced by resveratrol administration to rats has shown to be protective against acute intestinal inflammation from colitis by downregulating inflammation via NF-κB." (PMID 33414704, 2020). "Recently, it has showed its protective effect in colitis mice by activating the SIRT1/FoxOs pathway." (PMID 31849652, 2019). "We would like to point out that these findings do not exclude the possibility that additional factors other than Smad7 contribute to reduce the mucosal levels of Sirt1 during colitis." (PMID 30147698, 2018). "Following DSS administration, Smad7 Tg mice develop a more severe colitis and exhibit a further reduction of the number of Sirt1-positive T cells when compared with WT mice." (PMID 30147698, 2018).
colitis (continued). "Given these last observations, we studied the impact of Sirt1 on the pathogenesis of both colitis and CAC." (PMID 25013930, 2014). "Indeed, CPE was also capable of stimulating sirtuin-1 (SIRT-1) in colonic tissues obtained from DSS-induced colitis mice, which is known to suppress inflammation and enhance intestinal barrier function." (PMID 42163411, 2026). "Investigating the SIRT1/STAT3 axis in colitis may provide critical insights for developing novel IBD therapies." (PMID 40672369, 2025). "Similarly, resveratrol, a pharmacological activator of SIRT1, which has anti-inflammatory properties, has been shown to combat inflammation in chemically induced colitis." (PMID 40613788, 2025). "SIRT1, which is closely associated with cellular metabolism and stress responses, also interacts with the STAT3 pathway, modulating the inflammatory process in colitis." (PMID 40672369, 2025). "To test if smooth muscle—particularly Sirt1-Tg smooth muscle—could play a role in intestinal injury responses, we used DSS to induce experimental colitis and compare WT to Sirt1-Tg mice." (PMID 40076434, 2025). "AMPK can form a positive feedback loop with its downstream target Sirt1 to ameliorate colitis." (PMID 38466649, 2024). "In intestinal, SIRT1 can promote the onset and progression of inflammatory bowel disease(IBD), loss of Sirt1 can increase the number of Paneth cells and goblet cells and alleviate colitis." (PMID 39867884, 2024). "Sirt1 activation effectively alleviated colitis in mice induced by dextran sulfate sodium." (PMID 38997964, 2024). "Moreover, it was recently reported that treatment with diosmin (DIO) against colitis counteracted colon oxidative damage and inflammation, through the upregulation of SIRT1 circular RNA (Circ-SIRT1)." (PMID 38396635, 2024). "The miR-31-5p antagomir may influence macrophage differentiation and immune function through AMPK/Sirt1-dependent signaling in colitis." (PMID 38466649, 2024). "SIRT1 gene deletion may help in maintaining gastrointestinal immune homeostasis to improve the disease status of colitis." (PMID 37483618, 2023). "The Inhibition of SIRT1 may reduce the severity of colitis by promoting the production of Foxp3+T-regulatory cells, as well as paneth and goblet cells, which play crucial roles in maintaining gastrointestinal homeostasis." (PMID 37720208, 2023). "Since activating SIRT1 could prevent and treat experimental colitis in mice, it could be used to treat IBD in humans." (PMID 37371959, 2023). "SIRT1 activators have recently been shown to protect against chemically-induced colitis." (PMID 37111290, 2023). "Thus, to validate our findings from the DSS colitis model and gain further insight into the importance of the SIRT1-PGC1α axis in colonic inflammation, we employed the C. rodentium-induced murine model of infectious colitis." (PMID 37744380, 2023). "Moreover, catalpol decreased the levels of miR132 and the acetylation levels of Heat Shock Factor protein 1 (HSF1), while it increased SIRT1 protein levels in the rat colitis model." (PMID 35883477, 2022). "In colitis mice, the expressions of SIRT1, FOXO1, FOXO3α, and FOXO4 could be increased by salidroside to attenuate inflammation reaction." (PMID 35479323, 2022). "Literature data provided a valuable overview of the NF-κB/Nrf2/SIRT1 signaling target as a new strategy to counteract colitis, highlighting its pivotal role in IBDs and emphasizing the inhibition of NF-κB translocation and the modulation of Nrf2/SIRT1 signal through supplements or natural compounds." (PMID 35893393, 2022).
colitis (continued). "In fact, we observed that DNBS-induced colitis affects the antioxidant response by SIRT1 depletion, as a result of slight binding activity of the nuclear transcriptional factor Nrf2 and reduced cytosolic expressions of antioxidant enzymes such as HO-1 and Mn-SOD." (PMID 35893393, 2022). "Downsized SIRT1 expression can aggravate the occurrence of colitis." (PMID 35958178, 2022). "Thus, the authors suggested that loganin attenuates DSS-induced colitis by modulating SIRT1/NF-κB pathway." (PMID 35883477, 2022). "Thus, the results suggest that catalpol ameliorates colitis by modulating the miR132/SIRT1/HSF1 signaling pathway." (PMID 35883477, 2022). "DSS did not induce colitis successfully in SIRT1-deficient mice with decreased expression of inflammatory genes." (PMID 34887866, 2021). "Taken together, SIRT1 activation attenuates colitis, and SIRT1 may represent a promising target for treating IBD." (PMID 34887866, 2021). "In one study, intestinal-specific deletion of SIRT1 protected mice from the development of colitis." (PMID 34887866, 2021). "Most of these metabolic pathways being impaired by colitis are SIRT1/PGC-1α- or LXRα-mediated ones." (PMID 33674694, 2021). "In summary, bergenin could ameliorate colitis in mice through inhibiting the activation of macrophages via regulating PPARγ/SIRT1/NF-κB-p65 pathway." (PMID 29375382, 2017). "In addition, GW9662 (1 mg/kg) obviously reversed bergenin-mediated inhibition of NF-κB-p65 acetylation and nuclear translocation, up-regulation of SIRT1 expression in colon tissues of colitis mice." (PMID 29375382, 2017). "Therefore, upregulation of circ-Sirt1 to increase Sirt1 signaling may be a potential strategy to counteract DSS-induced colitis." (PMID 38611801, 2024). "Thus, exogenous administration of SIRT1 activators reduced colitis." (PMID 37483618, 2023). "Thus, we subjected mice to a model of acute DSS colitis and assessed the expression of SIRT1." (PMID 37744380, 2023). "Based on our following studies, we now hypothesize that significantly decreased NAD+ levels within the intestinal epithelium during colitis renders SIRT1 unable to activate PGC1α, resulting in decreased mitochondrial biogenesis and subsequent mitochondrial dysfunction." (PMID 37744380, 2023). "Therefore, mice with DSS-induced colitis benefit from SIRT1 activation or SIRT6 overexpression." (PMID 37371959, 2023). "However, whether COS can alleviate colitis by activating the PPARγ/SIRT1-mediated NF-κB signaling pathway is still unclear." (PMID 35200626, 2022). "Altogether, it indicates that AMPK/SIRT1/PGC-1α may be a potential pathway mediating the protective effect of AT III on mitochondrial dysfunction in the intestinal epithelium of experimental colitis." (PMID 35431653, 2022). "The deletion of SIRT1 may inhibit the development of colitis through the induction of Tregs." (PMID 34887866, 2021). "This DSS-induced colitis-associated lipid metabolic dysfunction was most likely due to overall disruption of metabolic functions such as fatty acid oxidation, lipolysis, RCT, bile acid synthesis, and WAT browning and BAT thermogenesis, most of which are mediated via SIRT1/PGC-1α and LXRα." (PMID 33674694, 2021). "The results of the present study reveal that SMC-specific SIRT1 negatively regulates the colonic epithelium regeneration after injury, resulting in a delayed recovery following DSS-induced colitis." (PMID 40076434, 2025). "Here, we explored the role of SMC SIRT1 in colonic mucosa regeneration and recovery after DSS-induced colitis." (PMID 40076434, 2025). "In the current study, we evaluated the effect of smooth muscle SIRT1 on intestinal mucosal integrity and immune homeostasis using genetically modified mice by DSS treatment, a common approach to induce experimental colitis." (PMID 40076434, 2025).
colitis (continued). "According to many clinical and preclinical research, SIRT1 is decreased in UC patients or IBD models, and administration with SIRT1 inducers significantly reduces colitis severity." (PMID 38796570, 2024). "HFD feeding resulted in colitis: it elevated myeloperoxidase, TNF-α, IL-1β, and IL-6 levels, NF-κB activation (p-p65/p65), and NF-κB+CD11c+ cell number and decreased IL-10 and SIRT1 levels and AMPK activation (p-AMPK/AMPK) in the colon." (PMID 39599597, 2024). "To gain further insight into the crucial involvement of SIRT1 K408 acetylation in aspirin's anti‐inflammatory mechanisms, we conducted a study using both wild‐type (WT) and K408Q mutant mice in a DSS‐induced colitis murine model." (PMID 38482749, 2024). "EX-527 and Nolisoboldin suppressed SIRT1 expression and induced Treg differentiation in DSS-induced colitis mice." (PMID 37371959, 2023). "Elsewhere, it has been reported that Cay10591 activates SIRT1 and inhibits NF-κB signaling and inflammatory cytokine production in TNBS or oxazolidinone-induced mice colitis." (PMID 37371959, 2023). "Our data indicate that decreased NAD+ levels are responsible for decreased SIRT1 and PGC1α levels and increased mitochondrial dysfunction during DSS colitis." (PMID 37744380, 2023). "As such, we treated mice undergoing experimental colitis (both DSS colitis and infectious colitis) with the NAD+ precursor, NR, and assessed the effects of NR treatment on the SIRT1-PGC1α axis." (PMID 37744380, 2023). "Exacerbation of colitis is achieved through the inhibition of NF-κB/STAT3 signaling, and the activation of HO-1/Nrf2/SIRT1 pathways." (PMID 37359553, 2023). "Therefore, COS may prevent or treat colitis by suppressing the production of inflammatory factors, preventing the inflammation response via activating PPARγ and SIRT1, inhibiting the acetylation and phosphorylation of NF-κB p65, and optimizing the intestinal microbiota composition." (PMID 35200626, 2022). "To explore the potential molecular mechanism of COS in alleviating colitis, we tested the effect of COS on PPARγ/SIRT1 and NF-κB signaling pathway in LPS-stimulated RAW 264.7 cells and in the colonic tissues of DSS-induced colitis mice." (PMID 35200626, 2022). "For example, Bergenin restrained the activation of macrophages by modulating the PPARγ/SIRT1/NF‐κB‐p65 pathway, thereby ameliorating DSS‐triggered colitis in mice." (PMID 35524480, 2022). "We observed that SIRT1 expression was significantly downregulated in the liver, SAT, and BAT of DSS-induced colitis mice, which was accompanied by suppressed expression of fatty acid oxidation genes in the liver, SAT, and MAT." (PMID 33674694, 2021). "However, although SIRT1 has been intensively studied as a master regulator in the pathogenesis of chronic inflammation-related metabolic complications, it has not been known whether its dysfunction is associated with DSS-induced colitis." (PMID 33674694, 2021). "Previous studies demonstrated that the activation of SIRT1/PGC-1α dependent pathway by SRT170 upregulated tight junction molecules in porcine intestinal epithelial cells and in a murine colitis model." (PMID 33607992, 2021). "Since high Smad7 contributes to amplify inflammatory signals in experimental models of colitis and IBD mucosa, we tested the possibility that Smad7 can negatively regulate Sirt1 expression." (PMID 30147698, 2018). "In conclusion, NOR promoted Treg differentiation and then alleviated the development of colitis by regulating AhR/glycolysis axis and subsequent NAD+/SIRT1/SUV39H1/H3K9me3 signaling pathway." (PMID 29449535, 2018). "Consistently, mucosal T cells of Smad7-transgenic mice contained reduced levels of Sirt1, a defect that was amplified by induction of DSS colitis." (PMID 30147698, 2018). "In this study, we aimed to investigate whether Eng alleviates experimental colitis by restoring mitochondrial function and intestinal barrier integrity via the AMPK/SIRT1/PGC-1α pathway." (PMID 40427406, 2025).